SHANK2 (SH3 and multiple ankyrin repeat domains 2)
Diseases named in the same sentence as SHANK2 in open-access papers (continued):
Sharing a sentence is not in itself a finding about the gene and the disease.
autism spectrum disorder (49 papers, 2012 to 2025). A spectrum of developmental disorders that includes autism, and Asperger syndrome. "SHANK2 disorder is a rare neurodevelopmental disorder caused by a deletion or pathogenic sequence variant of the SHANK2 gene and is associated with autism spectrum disorder (ASD), intellectual disability (ID), and developmental delay." (PMID 40307697, 2025). "Variations or microdeletions in the SHANK2 gene have been linked to a variety of neurodevelopmental disorders, including autism spectrum disorders (ASD) and mild to moderate intellectual disability (ID) in human." (PMID 38075274, 2023). "Our work suggests that the higher fracture risk in patients with autism spectrum disorders (ASD) due to loss of Shank protein expression depends at least in part on the role of Shank2 in bone." (PMID 36751416, 2022). "Genetic defects in the SHANK2 gene, encoding for synaptic scaffolding protein, are associated with a variety of neurodevelopmental conditions, including autism spectrum disorders and mild to moderate intellectual disability." (PMID 35456494, 2022). "Among the three known Shank family proteins, Shank2 and Shank3 have been associated with various brain disorders, including autism spectrum disorder (ASD), Phelan-McDermid syndrome, intellectual disability, and schizophrenia." (PMID 36311023, 2022). "Deleterious de novo SHANK2 mutations have been identified in individuals with intellectual disability (ID), autism spectrum disorders (ASD), developmental delay, and attention deficit and hyperactivity disorder." (PMID 33483523, 2021). "SHANK2 (ProSAP1) is a postsynaptic scaffolding protein of excitatory synapses in the central nervous system and implicated in the development of autism spectrum disorders (ASD)." (PMID 34899182, 2021). "SHANK2 mutations have been identified in individuals with neurodevelopmental disorders, including intellectual disability and autism spectrum disorders (ASD)." (PMID 33483523, 2021). "Shank2 is an excitatory postsynaptic scaffolding protein strongly implicated in autism spectrum disorders (ASDs)." (PMID 34594187, 2021). "Shank2 is an abundant postsynaptic scaffolding protein implicated in neurodevelopmental and psychiatric disorders, including autism spectrum disorders (ASD)." (PMID 29970987, 2018). "Loss-of-function mutations in the gene encoding the postsynaptic scaffolding protein SHANK2 are a highly penetrant cause of autism spectrum disorders (ASD) involving cerebellum-related motor problems." (PMID 27581745, 2016). "However, information is lacking on the distribution of many other components, such as Shank2, a postsynaptic scaffolding protein whose cerebellar dysfunction is associated with autism spectrum disorders." (PMID 38783902, 2024). "Mutations of the postsynaptic scaffold protein Shank2 lead to autism spectrum disorders (ASD)." (PMID 36751416, 2022). "Shank2 is an abundant postsynaptic scaffolding protein that is known to regulate excitatory synapse assembly and synaptic transmission and has been implicated in various neurodevelopmental disorders, including autism spectrum disorders (ASD)." (PMID 34177464, 2021). "Moreover, a mutation in SHANK2 found in autism spectrum disorders (ASDs) similarly disrupts these processes." (PMID 31597090, 2019). "In addition, mutations in the Shank2 gene have been identified in individuals with autism spectrum disorders and mental retardation." (PMID 28484738, 2017). "Mutations in SHANK2 are associated with autism spectrum disorders (ASD)." (PMID 27581745, 2016). "The genes Shank1 and Shank2 (containing 74 and 394 pG4-BS regions, respectively) encode proteins that are members of the Shank family of proteins functioning as molecular scaffolds in excitatory synapses, and whose deletion was associated with increased susceptibility to autism spectrum disorder." (PMID 37094040, 2023).
autism spectrum disorder (continued). "Shank2 is an abundant excitatory postsynaptic scaffolding protein that has been implicated in various neurodevelopmental and psychiatric disorders, including autism spectrum disorder (ASD), intellectual disability, attention-deficit/hyperactivity disorder, and schizophrenia." (PMID 36311025, 2022). "Furthermore, mice deficient in the postsynaptic scaffolding protein Shank2, a mouse model of autism spectrum disorder that exhibits impaired spatial learning in the Morris water maze, also exhibited impaired learning and relearning of cued goal localization in VR." (PMID 28484738, 2017). "Previous genetic studies have identified shared genetic variants in both schizophrenia and autism spectrum disorders (e.g., neurexin family gene, CNTNP2, SHANK2 gene)." (PMID 37484674, 2023). "Mutations within the SHANK family of genes (comprising SHANK1, PROSAP1/SHANK2 and PROSAP2/SHANK3) are over-represented in the autism spectrum disorder (ASD) population and are the cause of specific disorders such as Phelan-McDermid Syndrome." (PMID 29970986, 2018). "Although no study has focused on SHANK2 hypomethylation, mutation and copy number variation of SHANK2, encoding a member of synaptic scaffolding protein in the SHANK family was reported in patients with autism spectrum disorder and mental retardation." (PMID 29618728, 2018). "Mutations in SHANK genes, in particular SHANK2 and SHANK3, lead to autism spectrum disorders (ASD) in both human and mouse models." (PMID 27795858, 2016). "Finally, a study assessed two different types of mice (Shank2 and Shank3) in an autism spectrum disorder model, in which mice had to coordinate their running through a maze to receive a reward." (PMID 39509367, 2024). "Mutations in the SHANK2 gene have been associated with both ADHD and autism spectrum disorder." (PMID 37147306, 2023). "Moreover, SHANK2 knock-out mice showed reduced tactile perception and analgesia to chronic pain in autism spectrum disorder." (PMID 37303955, 2023). "SHANK2, a highly polymorphic gene containing SNPs, small indels, SVs, and TRs (Table SM4) can be proposed as a relevant gene candidate as mutations in this gene have been associated with the autism spectrum disorder in humans." (PMID 36057580, 2022). "Several genes were validated in APA sperm that were associated with autism spectrum disorder (CACNA1H, CNTNAP2, GRIN1, SHANK2, SHANK3, ZNF804A), schizophrenia (TCF3, ZNF804A), and bipolar disorder (COMT, DRD4, GRIN1, MBP, PRKCZ, SHANK2, TRPM2, ZNF804A), and in APA blastocysts (CACNA1H)." (PMID 32610362, 2020). "Moreover, SHANK2 and SHANK3 have been shown to be causative genes for autism spectrum disorders, possibly through the regulation of RAC1 function." (PMID 32616021, 2020). "Genetic defects in the three SH3 and multiple ankyrin repeat domains (SHANK) genes (SHANK1, SHANK2, and SHANK3) are associated with multiple major neuropsychiatric disorders, including autism spectrum disorder (ASD), schizophrenia (SCZ), and bipolar disorder (BPD)." (PMID 30505269, 2018). "Similarly, we observed novel sex differences in the SHANK2 and SHANK3 scaffolding protein genes that have been associated with autism spectrum disorders." (PMID 26553366, 2015). "Additionally, we observed ectodermal EtOH-induced alterations in several genes, such as LHX2, SHANK2, TRIO, ZMYND8, ARX, NRXN3 and SEMA5A, that have also been associated with autism spectrum disorder (ASD) (SFARI Gene Database, 2024; accessed: 1, August, 2024)." (PMID 40401629, 2025). "Moreover, Shank2 proteins play an important role in NMDA receptors-mediated pain hypersensitivity such that Shank2 mutations may suppress NMDA-ERK signaling in pain transmission, and this interaction has been liked to self-injurious behaviors in autism spectrum disorder." (PMID 34680965, 2021).
schizophrenia (31 papers, 2014 to 2024). A major psychotic disorder characterized by abnormalities in the perception or expression of reality. "We included PDZ domain variants identified in individuals with schizophrenia, i.e., p.S610Y (in the extended binding site on Shank2) and p.N690S." (PMID 36450866, 2024). "Human genetic studies have implicated aberrant expression of SHANK2 in phenotypes such as intellectual disability, schizophrenia, and bipolar disorders." (PMID 32616021, 2020). "Peykov and colleagues identified a rare causative SHANK2 variant (SHANK2A1731S) in schizophrenia, and several groups have found missense mutations in SHANK3 in schizophrenia." (PMID 33343614, 2020). "SHANK2 has been implicated in various brain disorders, including ASD, ID, DD, ADHD, schizophrenia, epilepsy, and obsessive–compulsive disorder." (PMID 37805537, 2023). "Despite the relevance of SHANK2 in ASDs, ID, and schizophrenia, most ground-lying studies on protein expression have been conducted in model organisms." (PMID 37953224, 2023). "Some of the connected genes like PRKCZ, SHANK2, ZNF608, and PRDM16 were also identified as schizophrenia risk factors." (PMID 36259657, 2022). "Intriguingly, mutations in SHANK2 are associated with ASD, neurodevelopmental disorders, and neuropsychiatric disorders, such as intellectual disability and schizophrenia." (PMID 32560273, 2020). "In individuals with ASD or schizophrenia patients with ASD traits, mutations were repeatedly reported for all SHANK gene family members, namely SHANK1, SHANK2 and SHANK3." (PMID 26819149, 2016). "Both miRNAs overlapped by the 3q13.31 deletion in this patient (miR-4796, miR-568) have predicted targets that are additional candidate genes for schizophrenia and related disorders, including SHANK2 and FMR1." (PMID 24650298, 2014). "Our study provides evidence that a direct regulatory link exists between miR-137 and SHANK2 and supports the finding that miR-137 signaling might be altered in schizophrenia." (PMID 29665782, 2018).
Intellectual disability (29 papers, 2013 to 2025). "We describe two patients with de novo missense variants in SHANK2 affected by a severe neurodevelopmental disorder, comprising moderate intellectual disability, delayed acquisition of motor and language skills, but also seizures (patient 1) and microcephaly (patient 2)." (PMID 36450866, 2024). "To investigate the functional consequences of SHANK2 mutations that have been identified in patients with ASD and intellectual disability, we introduced SHANK2 frameshift mutations in SH-SY5Y cells using CRISPR/Cas9-based genome editing." (PMID 33483523, 2021). "Deleterious de novo SHANK2 mutations have always been identified in a heterozygous state in patients with ASD, intellectual disability, attention deficit and hyperactivity disorder as well as language impairment, with one allele unaffected." (PMID 33483523, 2021). "SHANK1 (0.04%) and SHANK2 (0.17%) mutations occurred less frequently and were present in individuals with ASD and normal IQ, and ASD with moderate intellectual disability." (PMID 28702161, 2017). "In addition, SHANK2 and SHANK3 mutations are tightly linked with intellectual disability, while SHANK1 mutations have been identified in ASD patients with normal intelligence." (PMID 34021263, 2021).
Anxiety (22 papers, 2013 to 2024). Intense feelings of nervousness, tension, or panic often arise in response to interpersonal stresses. "In our battery, Shank2-deficient mice exhibited anxiety-related behaviors, hyperactivity, and learning deficits." (PMID 39262819, 2024). "Since ASD is associated with atypical sensory responses and heightened anxiety, we examined whether WT and Shank2-KO mice show differential eye closure responses to an air puff." (PMID 36192805, 2022). "Anxiety-like behavior is also present in mice with Purkinje cell-specific deficiency of Shank2." (PMID 31511635, 2020). "Cerebellar Shank2 (an excitatory postsynaptic scaffolding protein) was proposed to regulate specific repetitive and anxiety-like behaviors." (PMID 36614124, 2022). "Restricting Shank2 deletion to the cerebellum results in enhanced repetitive and anxiety behaviours, linking ASD-associated mutations in Shank2 in the cerebellum with specific ASD behaviours." (PMID 35002604, 2021). "CQ rescues social interaction in Shank2−/− and Tbr1+/− mice, but it fails to rescue social novelty recognition, repetitive behaviour, hyperactivity or anxiety-like behaviour in Shank2−/− mice." (PMID 25981743, 2015). "And in respect with ASD-related genes, behavioral tests using the SHANK2-KO mouse model with exon 6–7 deleted showed a decrease in interaction and social communication, memory deficit and spatial learning, hyperactivity, and anxiety-related behavior." (PMID 36860270, 2023). "Notably, Shank2−/− mice spent less time in the centre region of the open-field arena, a measure of anxiety-like behaviour." (PMID 25981743, 2015). "Another example is the demonstration that CDPPB rescues only social interaction in Shank2-deficient mice but fails to rescue impaired pup retrieval, repetitive jumping, hyperactivity, and anxiety-like behavior." (PMID 23935565, 2013). "A similar deficit in spatial memory is seen in two Shank2 PDZ-deletion models, combined with increased self-grooming behavior and anxiety along with decreased social interaction or novelty." (PMID 35782388, 2022). "Furthermore, Shank2-deletion (Shank2−/−) mouse models of ASD have been reported to present deficits in social interactions, reduced ultrasonic vocalizations, increased anxiety and hyperactivity." (PMID 38853567, 2024). "This stimulus restored social interaction in Shank2–/– mice without affecting locomotor activity or anxiety-like behavior." (PMID 34433814, 2021). "The absence of increased anxiety also hints at the presence of further modifying factors in S100B exposed mice or Shank2 and Shank3 KO mice that modulate the phenotype, such as extracerebral factors like gastrointestinal abnormalities that, for example, have been reported in Shank3 KO mouse models." (PMID 34741005, 2021). "Zinc mobilization has also been shown to restore glutamatergic synaptic transmission in the amygdala of Tbr1−/− ASD mice and in the hippocampus of Shank2−/− mice that was accompanied by a significant improvement in social interaction, but not anxiety behaviors, in both ASD mice models." (PMID 30405356, 2018).
epilepsy (9 papers, 2014 to 2025). A brain disorder characterized by episodes of abnormally increased neuronal discharge resulting in transient episodes of sensory or motor neurological dysfunction, or psychic dysfunction. "SHANK1, SHANK2, and SHANK3 variants have been associated with the development of ASDs, but they are also increasingly recognized as contributing to epilepsy, particularly through their role in synaptic excitability and plasticity." (PMID 39596051, 2024). "Looking into the DEG subnetwork, we found that some well-known ASD candidate genes, such as Kcnma1, Shank2, Cacna1a and Cacna1b, and epilepsy candidate genes, such as Scn3a, Grin2a, Gabrg2, and Grin2b, are hub genes in this subnetwork." (PMID 32033586, 2020).
Phelan-McDermid syndrome (8 papers, 2017 to 2024). A rare genetic neurodevelopmental disorder characterized by neonatal hypotonia, global developmental delay, normal to accelerated growth, absent to severely delayed speech, and minor dysmorphic features. "Human genetic studies have strongly linked Shank genes, including Shank1, Shank2, and Shank3, with Phelan-McDermid syndrome (PMS), ASD, AD, and SCZ associated with ID." (PMID 28331639, 2017).
bipolar disorder (7 papers, 2018 to 2025). A disorder of the brain that causes unusual shifts in mood, energy, activity levels and the ability to carry out day-to-day tasks. "Based on hub genes, 49 diseases were predicted by DisGeNET, bipolar disorder was disease predicting by SHANK2 and TGM2 simultaneously." (PMID 41142802, 2025).
Cognitive impairment (7 papers, 2014 to 2023). Abnormal cognition is characterized by deficits in thinking, reasoning, or remembering. "The degree of related mutations and cognitive impairment between SHANK1-3 also differs: patients with SHANK3 mutations suffer more cognitive impairment than those with SHANK1 or SHANK2 mutations." (PMID 36846568, 2023). "Shank2 knockout mice and rats have been generated, which show hyperactivity, repetitive behavior as well as social and cognitive impairments together with impaired synaptic transmission." (PMID 33483523, 2021). "In the homozygous Shank2 knockout mice, cognitive impairments as well as a disturbed synaptic signal transmission have been observed." (PMID 33483523, 2021).
developmental delay (7 papers, 2012 to 2025). "Human individuals with heterozygous deleterious de novo SHANK2 mutations show a general developmental delay with delayed development of speech as well as learning impairments and mild to severe intellectual disability." (PMID 33483523, 2021). "A DNA hypermethylation value of 5 CpG positions within the SHANK2 gene was found in a male patient with ID and developmental delay, suggesting that SHANK2 expression is sensitive to the DNA methylation pattern." (PMID 30072871, 2018).
neuroblastoma (7 papers, 2018 to 2023). Neuroblastoma (NB) is the most common solid, extracranial childhood tumor. "The intrinsic biological variation of the neuroblastoma cell population is likely to mask low effects resulting from SHANK2 mutations, especially in the heterozygous state." (PMID 33483523, 2021). "In this study, the molecular and cellular consequences of mono-allelic and bi-allelic SHANK2 frameshift mutations were investigated in the neuroblastoma cell line SH-SY5Y." (PMID 33483523, 2021). "SHANK2, which encodes a post-synaptic protein, is disrupted in 14% of 11q-deleted high-risk neuroblastoma." (PMID 34885007, 2021). "Furthermore, SHANK2 is frequently downregulated in neuroblastoma, and its decreased expression is associated with a poor survival of patients." (PMID 36231770, 2022). "In this study we employed the human neuroblastoma cell line SH-SY5Y to model SHANK2 variants." (PMID 33483523, 2021). "Human neuroblastoma cells (SH-SY5Y) were transfected with a dual luciferase reporter plasmid (psiCHECKTM-2) containing either the wild type (wt) SHANK2 3′UTR sequence or a miR-137 binding site-mutated 3′UTR (mut) together with either miR-137 or negative control miRNA mimics." (PMID 29665782, 2018). "On the other hand, overexpression of SHANK2 in neuroblastoma cells results in increased cell differentiation and reduced cell growth following treatment with all-trans retinoic acid." (PMID 36231770, 2022). "Further, overexpression of SHANK2 resulted in inhibition of neuroblastoma cell growth, as well as increased differentiation upon treatment with retinoic acid." (PMID 34885007, 2021). "This may point to a role of SHANK2 regarding the switch from proliferation to differentiation during the early neuronal differentiation process in neuroblastoma cells." (PMID 33483523, 2021). "Interestingly, both SHANK2 and DLG2 are post-synaptic anchor proteins that are both able to modulate transcriptional outcome in neuroblastoma cells from proliferation cues to differentiation cues." (PMID 34885007, 2021). "Moreover, by whole exome sequencing, we demonstrated that NB exo-DNA represents the entire exome and that it carries tumor-specific genetic mutations, including those occurring on known oncogenes and tumor suppressor genes in neuroblastoma (ALK, CHD5, SHANK2, PHOX2B, TERT, FGFR1, and BRAF)." (PMID 33915956, 2021).